P2RX2 (purinergic receptor P2X 2)
Description:
ATP-gated nonselective transmembrane cation channel permeable to potassium, sodium and calcium. Activation by extracellular ATP induces a variety of cellular responses, such as excitatory postsynaptic responses in sensory neurons, neuromuscular junctions (NMJ) formation, hearing, perception of taste and peristalsis (By similarity). In the inner ear, regulates sound transduction and auditory neurotransmission, outer hair cell electromotility, inner ear gap junctions, and K(+) recycling. Mediates synaptic transmission between neurons and from neurons to smooth muscle (By similarity).
Synonyms: P2X2; DFNA41
Tractability: Small molecule: a high-quality ligand is known; it belongs to a druggable protein family. Antibody: UniProt places it where antibodies can reach, with high confidence; its Gene Ontology location is reachable by antibodies, with high confidence; UniProt predicts a signal peptide or a membrane-spanning region. PROTAC: ubiquitination databases record sites on it; a small molecule that binds it is known.
Target class: Ligand-gated ion channel; P2X receptor; Ion channel
Safety:
Unwanted effects reported when the protein is acted on. In parentheses: how it was acted on, where the effect was seen, and who reports it.
decreased convulsions (inhibition, acute dosing; nervous system, renal, immune; source: Lynch et al. (2017))
decreased inflammation (inhibition, acute dosing; nervous system, renal, immune; source: Lynch et al. (2017))
decreased pain (inhibition, acute dosing; nervous system, renal, immune; source: Lynch et al. (2017))
hemolysis (activation, acute dosing; nervous system, renal, immune; source: Lynch et al. (2017))
increased pain (activation, acute dosing; nervous system, renal, immune; source: Lynch et al. (2017))
increased urinary sodium excretion (activation, acute dosing; nervous system, renal, immune; source: Lynch et al. (2017))
increased urine excretion (activation, acute dosing; nervous system, renal, immune; source: Lynch et al. (2017))
neurodegeneration (activation, chronic dosing; nervous system, renal, immune; source: Lynch et al. (2017))
Gene: Protein-coding gene on chromosome 12 (132,618,776 to 132,622,388, forward strand). Ensembl gene ENSG00000187848.
Subcellular location: Cell membrane
Pathways (Reactome):
Hemostasis: Elevation of cytosolic Ca2+ levels; Platelet homeostasis
Gene Ontology:
Molecular function: extracellularly ATP-gated monoatomic cation channel activity; identical protein binding; ATP binding; ligand-gated monoatomic ion channel activity; purinergic nucleotide receptor activity; monoatomic ion channel activity
Biological process: sensory perception of sound; calcium ion transmembrane transport; positive regulation of calcium ion transport into cytosol; positive regulation of calcium-mediated signaling; response to ischemia; excitatory postsynaptic potential; monoatomic cation transmembrane transport; monoatomic ion transport; purinergic nucleotide receptor signaling pathway; response to ATP
Cellular component: apical plasma membrane; plasma membrane; receptor complex; neuronal cell body; membrane; neuronal dense core vesicle; postsynapse
Genetic constraint (gnomAD): Loss-of-function variants: 50 observed, 49.6 expected, observed/expected ratio (o/e) 1.01, 90% interval 0.8 to 1.28. The upper end of that interval is the gene's LOEUF score, 1.28, which puts it in group 5 of 6, group 1 being the genes least tolerant of losing a copy. Missense variants: 658 observed, 603.65 expected, observed/expected ratio (o/e) 1.09, 90% interval 1.02 to 1.16. Synonymous variants: 289 observed, 242.43 expected, observed/expected ratio (o/e) 1.19, 90% interval 1.08 to 1.31.
Gene-disease validity (ClinGen):
ClinGen rates the evidence that P2RX2 causes each of these diseases.
nonsyndromic genetic hearing loss (autosomal dominant): Moderate. A disease characterized by hearing loss that is not part of a larger syndrome.
Homologues: Orthologues: chimpanzee P2RX2 (99% identical), macaque P2RX2 (97% identical), rat P2rx2 (80% identical), mouse P2rx2 (80% identical), dog P2RX2 (77% identical), pig P2RX2 (74% identical), guinea pig P2RX2 (74% identical), rabbit P2RX2 (68% identical), zebrafish p2rx2 (45% identical), tropical clawed frog p2rx2 (44% identical). Paralogues in human: P2RX3 (40% identical), P2RX4 (38% identical), P2RX5 (34% identical), P2RX6 (33% identical), P2RX1 (32% identical), P2RX7 (30% identical).
Diseases named in the same sentence as P2RX2 in open-access papers:
P2RX2 is named in the same sentence as 46 diseases in open-access papers, as found by Europe PMC text mining. Sharing a sentence is not in itself a finding about the gene and the disease. The quoted sentences say what the papers report.
hearing loss (8 papers, 2014 to 2025). "Normothermia TTM upregulated 13 genes associated with hearing loss, including Loxhd1, Tecta, Zmiz1, Espn, Gjb2, Sesn3, Bdp1, Hg, Pax3, Rnls, Syne4, P2rx2, and Pou3f4." (PMID 38298897, 2023). "Understanding the mechanisms through which these mutations affect the normal function and activation of P2RX2 will help in designing novel treatment modalities against hearing loss." (PMID 27252659, 2016). "Interestingly, one of the closely related family members of P2rx3, P2rx2, has been implicated in hearing loss associated with DFNA41." (PMID 32675174, 2020).
deafness (5 papers, 2016 to 2024). An inherited or acquired condition characterized by the complete loss of the ability to hear from one or both ears. "Generally, it seems that this substitution could have a key function in the P2RX2 protein, and mutations at this site give rise to pathogenicity and deafness." (PMID 34425661, 2021).
autosomal dominant deafness (4 papers, 2017 to 2026). "In humans, the pathological variation of the P2RX2 gene has been identified as the cause of autosomal dominant non-syndromic deafness, DFNA41." (PMID 41572111, 2026).
presbycusis (4 papers, 2018 to 2022). Bilateral hearing loss caused by progressive degeneration of cochlear structures and central auditory pathways, typically associated with the aging process. "Moreover, hypermethylation of CpG sites in the promoter region of SLC26A4 (DFNB4) and P2RX2 (DFNA41) genes resulted in increased risk for presbycusis in men, and a down-expression in elderly women with presbycusis, respectively." (PMID 30131691, 2018). "In addition, reduced expression of P2RX2, KCNQ5, ERBB3, and SOCS3 genes through DNA hypermethylation in elderly women was associated with presbycusis." (PMID 31947524, 2020).
prostate carcinoma (3 papers, 2022 to 2023). A carcinoma that arises from epithelial cells of the prostate gland. "In this study, we performed an integrated analysis of transcriptional, clinical, and somatic mutation data from The Cancer Genome Atlas database and identified the hub calcium channel-related gene P2RX2 to be associated with the prognosis and immune infiltration of prostate cancer." (PMID 36246559, 2022). "In conclusion, we revealed an association between calcium channel-related genes and prostate cancer, and identified P2RX2 as a biomarker for early diagnosis, prognosis prediction, and aiding treatment decisions for patients with prostate cancer." (PMID 36246559, 2022). "P2RX2 expression was positively correlated with immune cell infiltration levels and the expression of immune checkpoint genes, and downregulation of P2RX2 led to poor survival in patients with prostate cancer." (PMID 36246559, 2022).
developmental delay (1 paper, 2020). "Among these P2RX2 and ACADS are noteworthy for the developmental delay and behavioral and social problems presented in our patient." (PMID 32578677, 2020).
hearing disorder (1 paper, 2024). A disorder characterized by the partial or complete loss of the ability to detect sounds due to damage to the ear structures or inability of the brain to properly interpret or process the auditory signals it receives from the anatomic structures of the ear. "Proteins involved in specific forms of hearing disorders as a result of mutations (e.g., P2RX2) are also not part of the PPI network." (PMID 39062188, 2024).
lung carcinoma (1 paper, 2020). "We also showed that contrast with the unfavorable prognosis of pyrimidine metabolic rate–limiting enzymes, purinergic receptors P2RX1, P2RX2, P2RX7, P2RY12, P2RY13, and P2RY14 were favorable prognostic markers in patients with lung cancer." (PMID 32638267, 2020).
cancer (8 papers, 2014 to 2024). A tumor composed of atypical neoplastic, often pleomorphic cells that invade other tissues. "Moreover, we performed pan-cancer and drug sensitivity analyses of P2RX2 for better clinical applications." (PMID 36246559, 2022). "The results indicated that the downregulation of P2RX2 may activate pathways promoting cancer progression, such as the PI3K − Akt, NF − kappa B, and JAK − STAT signaling pathways." (PMID 36246559, 2022). "The mRNA expression of P2RX2 in human cancers was analyzed using the TIMER online database." (PMID 36246559, 2022). "Finally, we conducted a pan-cancer analysis, and the results indicated that P2RX2 is differentially expressed in several cancers, such as BLCA, COAD, KIRC, LUAD, and PAAD." (PMID 36246559, 2022).
tumor (3 papers, 2014 to 2022). "Second, the effect of P2RX2 on tumor immune infiltration should be further validated by molecular and animal experiments." (PMID 36246559, 2022). "To validate the role of P2RX2 as a tumor suppressor gene in PCa, we overexpressed P2RX2 in PCa cell lines by transfecting plasmids and verified the upregulation of P2RX2 using western blotting." (PMID 36246559, 2022). "Hence, P2RX2 may play an instrumental role in tumor immunity and act as a therapeutic target to enhance patient response to immunotherapy in PCa." (PMID 36246559, 2022). "To uncover the clinical relevance of P2RX2, we first used GEPIA to compare its expression between tumor and normal tissues, and the results matching GTEx demonstrated that the expression of P2RX2 was very low in PCa." (PMID 36246559, 2022).
P2RX2 also shares sentences with these, for which no sentence is quoted: depression (5 papers); diabetes (3); overactive bladder (3); epilepsy (2); myocardial ischemia (2); Alzheimer disease (1); bacterial infection (1); bone cancer (1); channelopathies (1); Cough (1); diabetic neuropathies (1); Duchenne muscular dystrophy (1); embryonal carcinoma (1); endometriosis (1); gastroesophageal reflux disease (1); gout (1); head and neck cancer (1); heart failure (1); hepatocellular carcinoma (1); infarction (1); infection (1); injury (1); lung diseases (1); male infertility (1); migraine (1); mood disorder (1); myocardial infarction (1); neuropathic pain (1); Obesity (1); osteoporosis (1).
A further 6 diseases each share a sentence with P2RX2 in 1 paper.